FAM216B (family with sequence similarity 216 member B)
Synonyms: C13orf30; FLJ40919
Tractability: No criterion of Open Targets' tractability assessment is met for any kind of drug.
Gene: Protein-coding gene on chromosome 13 (42,781,550 to 42,791,549, forward strand). Ensembl gene ENSG00000179813.
Genetic constraint (gnomAD): Loss-of-function variants: 9 observed, 12.49 expected, observed/expected ratio (o/e) 0.72, 90% interval 0.43 to 1.26. The upper end of that interval is the gene's LOEUF score, 1.26, which puts it in group 5 of 6, group 1 being the genes least tolerant of losing a copy. Missense variants: 164 observed, 166.62 expected, observed/expected ratio (o/e) 0.98, 90% interval 0.87 to 1.12. Synonymous variants: 50 observed, 57.5 expected, observed/expected ratio (o/e) 0.87, 90% interval 0.69 to 1.1.
Homologues: Orthologues: chimpanzee FAM216B (100% identical), macaque FAM216B (96% identical), pig FAM216B (73% identical), dog FAM216B (70% identical), rat Fam216b (54% identical), mouse Fam216b (53% identical). Paralogues in human: FAM216A (26% identical).
Diseases named in the same sentence as FAM216B in open-access papers:
FAM216B is named in the same sentence as 1 disease in open-access papers, as found by Europe PMC text mining. Sharing a sentence is not in itself a finding about the gene and the disease. The quoted sentences say what the papers report.
neoplasia (1 paper, 2026). "In the case of phaCin-β, 14 showed a higher prevalence in neoplasia cases flanking three genes: DOCK8 (dedicator of cytokinesis 8), FAM216B (family with sequence similarity 216 member B), and Vmn2r65 (vomeronasal 2, receptor 65)." (PMID 41513643, 2026).